CD69 (CD69 molecule)
Description:
Transmembrane protein expressed mainly on T-cells resident in mucosa that plays an essential role in immune cell homeostasis. Rapidly expressed on the surface of platelets, T-lymphocytes and NK cells upon activation by various stimuli, such as antigen recognition or cytokine signaling, stimulates different signaling pathways in different cell types. Negatively regulates Th17 cell differentiation through its carbohydrate dependent interaction with galectin-1/LGALS1 present on immature dendritic cells. Association of CD69 cytoplasmic tail with the JAK3/STAT5 signaling pathway regulates the transcription of RORgamma/RORC and, consequently, differentiation toward the Th17 lineage (By similarity). Also acts via the S100A8/S100A9 complex present on peripheral blood mononuclear cells to promote the conversion of naive CD4 T-cells into regulatory T-cells. Acts as an oxidized low-density lipoprotein (oxLDL) receptor in CD4 T-lymphocytes and negatively regulates the inflammatory response by inducing the expression of PDCD1 through the activation of NFAT. Participates in adipose tissue-derived mesenchymal stem cells (ASCs)-mediated protection against P.aeruginosa infection. Mechanistically, specifically recognizes P.aeruginosa to promote ERK1 activation, followed by granulocyte-macrophage colony-stimulating factor (GM-CSF) and other inflammatory cytokines secretion. In eosinophils, induces IL-10 production through the ERK1/2 pathway (By similarity). Negatively regulates the chemotactic responses of effector lymphocytes and dendritic cells (DCs) to sphingosine 1 phosphate/S1P by acting as a S1PR1 receptor agonist and facilitating the internalization and degradation of the receptor.
Synonyms: AIM; CLEC2C; BL-AC/P26; EA1; GP32/28; MLR-3
Tractability: Small molecule: a high-quality ligand is known. Antibody: UniProt places it where antibodies can reach, with high confidence; its Gene Ontology location is reachable by antibodies, with high confidence; UniProt predicts a signal peptide or a membrane-spanning region. PROTAC: a small molecule that binds it is known.
Target class: Membrane receptor
Gene: Protein-coding gene on chromosome 12 (9,752,486 to 9,760,901, reverse strand). Ensembl gene ENSG00000110848.
Subcellular location: Cell membrane
Gene Ontology:
Molecular function: identical protein binding; molecular sequestering activity; protein binding; transmembrane signaling receptor activity
Biological process: negative regulation of inflammatory response; negative regulation of T cell migration; negative regulation of T-helper 17 cell lineage commitment; cellular response to xenobiotic stimulus
Cellular component: plasma membrane; protein-containing complex; cell surface; external side of plasma membrane
Genetic constraint (gnomAD): Loss-of-function variants: 4 observed, 10.64 expected, observed/expected ratio (o/e) 0.38, 90% interval 0.18 to 0.86. The synonymous counts are far from expectation, so gnomAD's model fits this gene poorly and the ratio says little. Missense variants: 84 observed, 103.02 expected, observed/expected ratio (o/e) 0.82, 90% interval 0.68 to 0.98. Synonymous variants: 22 observed, 35.64 expected, observed/expected ratio (o/e) 0.62, 90% interval 0.44 to 0.88.
Homologues: Orthologues: chimpanzee CD69 (99% identical), macaque CD69 (68% identical), pig CD69 (66% identical), dog CD69 (66% identical), guinea pig CD69 (64% identical), rabbit CD69 (63% identical), rat Cd69 (59% identical), mouse Cd69 (58% identical), zebrafish si:ch211-170d8.8 (23% identical), Drosophila melanogaster rgn (20% identical), zebrafish si:dkey-26c10.5 (20% identical), zebrafish si:ch211-193e13.5 (18% identical), and 2 more. Paralogues in human: CLEC2A (28% identical), CLEC2D (28% identical), CLEC2L (25% identical), CLEC2B (22% identical), CLEC9A (21% identical), KLRC2 (20% identical), KLRC3 (20% identical), KLRG1 (20% identical), KLRG2 (20% identical), KLRB1 (19% identical), KLRC1 (19% identical), CLEC5A (19% identical), and 11 more.
Diseases named in the same sentence as CD69 in open-access papers:
CD69 is named in the same sentence as 318 diseases in open-access papers, as found by Europe PMC text mining. Sharing a sentence is not in itself a finding about the gene and the disease. The quoted sentences say what the papers report.
COVID-19 (111 papers, 2020 to 2026). A disease caused by infection with severe acute respiratory syndrome coronavirus 2. "These high frequencies of activated HLA-DR+CD38+ T cells together with HLA-DR+ and CD69+ activated CD56dim NK cells were associated with acute COVID-19 and decreased with recovery in CONV." (PMID 34893580, 2021). "CD69 expression on MAIT cells has shown to be more pronounced in patients with detectable SARS-CoV-2 viremia, as well as in those with a more severe disease, suggesting a striking association between MAIT cells activation and worse clinical outcome." (PMID 35757770, 2022). "TCR clonotypes with sizes ranging from 2 to 5 were mainly concentrated in HLA_DR+ Tregs from the eight groups of COVID-19 patients, while in the healthy controls, these were enriched in the CD69+ Tregs." (PMID 40114921, 2025). "Considering the significant alterations of NKeff cells subset in COVID-19 patients, a detailed assessment of the immunophenotype of NKeff cells subset was conducted, focusing on markers including CD69, KIR, CD52, CD226, NKG2D, and CD62L using flow cytometry." (PMID 40471558, 2025). "Regarding to CD56dim CD16- cells subset, these cells of COVID-19 patients with T2D exhibited a higher CD69 expression and a lower NKG2D and CD62L expression in comparison with other groups." (PMID 40471558, 2025). "When CD69 + CD103 − T cells are apparent in elderly COVID-19 convalescents, they release more cytotoxic and inflammatory compounds, which is associated with deteriorating pathology and reduced lung function." (PMID 40644485, 2025). "For example, CD69 showed an AUC of only 0.568, possibly reflecting greater immune heterogeneity in COVID-19 brains." (PMID 41007696, 2025). "A significantly higher proportion of CD8+CD161+Vα7.2+ MAITs expressed proliferation marker Ki67 and activation marker CD69 in the acute samples indicating active proliferation and activation during acute COVID-19 as compared to convalescence." (PMID 38211733, 2024). "A sustained and significant increase of NK cells expressing the activation and tissue migration marker CD69 occurred in COVID-19 patients regardless disease severity in both the exhausted and effector NK-cell subpopulations compared to HD (p<0.001)." (PMID 39136010, 2024). "Prior findings reported that, in COVID-19, especially in severe patients, activation and exhaustion markers on the T cell surface were upregulated during acute infection, such as CD69, OX40, CD38, 4-1BB, PD-1, CTLA-4, LAG-3, TIM-3, and TIGIT." (PMID 39355257, 2024). "Meanwhile, an increase of CD4+ T cells expressing CD69+ together with CCL5 levels was noted in our experiments using bLf on COVID-19 samples." (PMID 39483459, 2024). "The CD4+CD38+ and CD8+CD69+ subsets accurately classified COVID-19 vs. healthy controls throughout the kinetic analysis." (PMID 39597661, 2024). "Both granzyme A and B positive CD8+ T cells were more activated (increased CD69 expression) in all COVID-19 patients compared to the control group." (PMID 39764446, 2024). "Overall, our findings demonstrated that, regardless of the time points along the timeline kinetics, CD4+CD38+ and CD8+CD69+ presented outstanding accuracy (AUC ≥ 0.9) in classifying COVID-19 patients vs. HCs." (PMID 39597661, 2024). "We then compared CD3+ cells isolated from COVID-19-infected subjects vs. healthy controls and found increased expression of activation markers including CD69, CD83, ICOS, RGS1 as well as other stress related genes including HIF1A, ATF4, NFKB1, and PR1." (PMID 36881624, 2023). "In our opinion, our study supports the superiority of CD40L/CD69 over the BAT in COVID-19 vaccine hypersensitivities during delayed reactions." (PMID 37686102, 2023). "The aim of this study was to evaluate a COVID-19 vaccine allergy using in vitro T-cell exposure to the tested drug with the flow cytometry measurement of CD69, CD40L, TNFa, IFNG, IL-2, IL-4, IL-6, IL-10, intracellular granulysin, and IFNgamma." (PMID 37686102, 2023).
COVID-19 (continued). "In contrast, both T cell populations in the paired COVID-19 dLNs showed classical activation markers, such as CD69, HLA-DR-DQ, ICOS and Ki67." (PMID 36774347, 2023). "Of importance, in these severely infected COVID-19 patients, the expression of CD69 in ILCs was higher, which as a marker for tissue homing and activation." (PMID 35967401, 2022). "Spike-specific CD69+4-1BB+CD8+ T cells were induced by the mRNA vaccine as in COVID-19 recovered individuals, and their frequencies were maintained for at least 12 weeks post second vaccination." (PMID 36685601, 2022). "ILCs-CD69+ increased and blood ILCs decreased in severe infections, indicating that severely infected COVID-19 patients have more lung homing and activation." (PMID 35967401, 2022). "Four Phenograph MAIT cell clusters were found to be overrepresented in patients who died of COVID-19 and these clusters were all characterised by high CD69 expression and low/very low levels of CXCR3." (PMID 34050887, 2022). "In influenza patients, the frequency of CD69+ NK cells was slightly higher in lung-homing receptor-negative NK cells, but overall higher than in COVID-19 patients." (PMID 35371005, 2022). "In COVID-19 patients CD69 expression was biased towards CD8+ T cells co-expressing lung-homing receptors." (PMID 35371005, 2022). "Our data are in line with other studies in which a higher representation of activated (CD69+) interferon-γ-producing CD4+ T-lymphocytes was detected in hospitalised COVID-19 patients with pneumonia." (PMID 36366522, 2022). "We found a significant increase in the expression of CD38 and CD69 in the active COVID-19 patients compared to the healthy and recovered, suggesting an activated T cell response." (PMID 36532041, 2022). "In both mild and severe cases of COVID-19, increased expression of the early activation marker CD69 on MAIT cells and diminished expression of the homing receptor chemokine C-X-C motif receptor 3 (CXCR3) has been reported." (PMID 34050887, 2022). "In COVID-19 patients, NK cells expressing these lung-homing receptors displayed higher expression of CD69 (on CD56brightCD16– and CD56dimCD16+ NK cells) and Ki67 (in CD56dimCD16+), as compared to lung-homing receptor-negative NK cells." (PMID 35371005, 2022). "Six hub genes (FCGR3A, CD69, IFNG, CCR7, CCL5, and CCL4) were closely associated with COVID-19 and HF." (PMID 36420258, 2022). "We defined the AIM+ cells as OX40+CD137+ for CD4+T cells and CD69+OX137+ for CD8+T cells following the method to identify SRAS-CoV-2 antigen-specific T cells in COVID-19 patients and vaccinated individuals." (PMID 35418996, 2022). "DC3 from COVID-19 patients, induced significantly less proliferation and CD69 expression in autologous T cells than DC3 of healthy donors irrespective of glucocorticoid therapy." (PMID 34614036, 2021). "In this study, we found the levels of CD69 expression to be significantly higher in severely affected COVID-19 patients." (PMID 34238985, 2021). "Activation of CD8 effector memory and central memory T cell were lower based on CD69 expression in older COVID-19 patients in the early phase of symptom onset." (PMID 34682920, 2021). "Of interest, an altered expression of various receptors involved in migration, adhesion and activation, including CXCR4, CD63 and CD69, have been reported in COVID-19, highlighting specific immunophenotypes with predictive potential for clinical outcomes." (PMID 34944610, 2021). "Within the BAL CD8+ T cell population, there appeared to be an enrichment of CD69+CD103− T cells in COVID-19 convalescents." (PMID 34591653, 2021). "T cells of patients with COVID-19 and acute malaria showed high frequencies of the activation markers CD69 and HLA-DR/CD38 as well as high frequencies of the inhibitory receptors LAG-3 and TIM-3." (PMID 32983106, 2020). "These CD4+ T-cells in COVID-19 patients have higher expression of CD69, CD38 and CD44 compared with healthy controls, indicating their activated status." (PMID 34676125, 2020).
COVID-19 (continued). "CD8+ T-cells in COVID-19 patients also showed activated phenotypes with higher expression of CD69, CD38 and CD44." (PMID 34676125, 2020). "CD8+ T cells from COVID-19 patients have a very marked activation phenotype with an increase in CD69, CD38, CD137, and CD44, especially in critically ill patients." (PMID 33193331, 2020). "In summary, the expression of activation markers (CD69, HLA-DR, CD38) on T cells was closely linked to the co-expression of inhibitory receptors (PD1, LAG-3, TIM-3) on T cells in COVID-19 and malaria patients." (PMID 32983106, 2020). "Overall, we observed a strong activation of T cells in COVID-19 and malaria with an increased expression of both early (CD69+) and late (HLA-DR+CD38+) activation markers as well as the co-stimulatory receptor CD226." (PMID 32983106, 2020). "Furthermore, when COVID-19 patients were compared with patients with T2D or control subjects, a trend was noted toward increased expression of CD69, KIR, and CD52 and decreased expression of CD226, NKG2D, and CD62L." (PMID 40471558, 2025). "Moreover, all COVID-19 patients showed a higher proportion of activated CD69+ exhausted and effector NK subpopulations compared to healthy controls, suggesting elevated cytotoxic activity of CD56dim NK cells." (PMID 39136010, 2024). "Finally, NK cells cocultured with monocytes from both moderate and severe COVID-19 patients had a higher proportion of activated (CD38+ CD69+) cells." (PMID 38578283, 2024). "CD69 is upregulated on the NK cells of severe COVID-19 patients and was significantly upregulated following coculture of healthy NK cells with severe COVID-19 patient monocytes in our study." (PMID 38578283, 2024). "Markers of activation CD38 and CD69 were more highly expressed on COVID-19 patient NK cells." (PMID 38578283, 2024). "Importantly, similar to our findings, severe COVID-19 was also associated with strongly increased protein expression of the activation markers CD38, CD69, and HLA-DR in early disease." (PMID 37712059, 2023). "This hypothesis is supported by the CD69 expression deficit in Th cells from COVID-19 patients that persisted when restricting the analysis to CD154+ AfuLy-reactive cells." (PMID 36052094, 2022). "Recently, we reported an association between CD69 expression on MAIT cells and COVID-19 outcome." (PMID 33763658, 2021). "Importantly, higher numbers of CD69+ peripheral blood MAIT cells in patients with COVID-19 on admission was predictive of the clinical course and disease severity." (PMID 34394094, 2021). "Thus, MAIT cell CD69 expression appears to be a robust and sensitive independent correlate of differential survival in critically ill COVID-19 patients." (PMID 34529726, 2021). "Moreover, both CD4+ and CD8+ T cells from COVID-19 patients overexpressed CD69 and TIM-3 compared with healthy controls, which is compatible with a hyperactivated pan T-cell exhaustion profile." (PMID 33060840, 2021). "Interestingly, the analysis of the relationship between CD69 and HLA-DR in COVID-19 patients showed that the frequency of PB NK cells expressing both surface antigens is increased in NK cells from COVID-19 patients with parallel increased molecule densities." (PMID 33861802, 2021). "Interestingly, there were statistically significant increments in CD56dim NK cell activation marker CD69 C-type lectin (p = 0.038) and in CD56dim NK cells expressing the checkpoint molecule PD-1 (p = 0.040) in COVID-19 patients with respect to controls." (PMID 34831404, 2021). "Therefore, interactions between NK cells and monocytes in the periphery may drive CD69 expression that leads to NK cell retention in the lungs during severe COVID-19." (PMID 38578283, 2024).
COVID-19 (continued). "The presence of cytoplasmic IFN-γ and TNF-α proteins, measured ex vivo, highly correlated with cell membrane expression of CD49a, CD69, and CD107a, raising the question whether these CD69+CD49a+CD107a+ cytokine-producing NK cells in severe COVID-19 patients represent a distinct subset of NK cells." (PMID 36275702, 2022). "Interestingly, CD69 expression on MAIT positively correlated with the level of plasmatic IL-18 that was significantly higher in the plasma of long-term ICU patients with fatal COVID-19 compared to plasma from patients hospitalized in an ICU or IDU." (PMID 35159352, 2022). "Furthermore, patients with COVID-19 had a significantly increased frequency of CD69+ eosinophils." (PMID 34548411, 2021). "In older individuals with COVID-19, phenotypic changes were noted, including increased expression of CD57 and CD69, indicators of overactivation, as well as up-regulation of PD-1 on NK cells." (PMID 40497938, 2025). "Our analysis revealed a trend towards elevated expression of CD69, KIR, and CD52, alongside diminished expression of CD226, NKG2D, and CD62L in patients who contracted COVID-19, when contrasted with those with T2D or control subjects." (PMID 40471558, 2025). "Later at D14–28, 16 cell subsets presented elevated global accuracy (AUC ≥ 0.8) to classify COVID-19 vs. HCs, with AUC = 1.0 registered for CD4+CD38+ and CD8+CD69+ and AUC = 0.9 observed for CD8+CD27+, CD3+CD107a+, CD4+T-bet+, CD8+CD107a+ and CD3+CD38+." (PMID 39597661, 2024). "Analysis of CD8+ T-cells showed that, despite the disease outcome, an increased frequency of CD69+ and CD107a+, along with a decreased percentage of CD28+, CD27+, and CD45RO+ CD8+ T-cell subsets, were observed in both COVID-19 subgroups." (PMID 39597661, 2024). "The most commonly used sets of markers for CD4 + T cells were OX40 and CD137, and CD69 and CD137 for CD8 + T cells in case of COVID-19 studies." (PMID 38167915, 2024). "Despite no changes in the frequency of CD8+ T-cells, increased frequencies of CD69+, CD107a+, T-bet+, and CD62L− and decreased percentages of CD28+, CD27+, and CD45RO+ CD8+ T-cells were observed for COVID-19 patients in comparison to HCs." (PMID 39597661, 2024). "Overall, our findings summarized a set of phenotypes feasible to be considered as potential predictors of COVID-19 outcome, including CD4+CD107a+, CD4+T-bet+, CD8+CD69+, CD8+T-bet+ and CD4+CD45RO+CD27+." (PMID 39597661, 2024). "The results demonstrated that, at D0, nine cell subsets presented robust global accuracy (AUC ≥ 0.8) to classify COVID-19 vs. HCs, with outstanding performance (AUC = 0.9) observed for CD8+CD69+, CD4+CD38+, CD3+CD38+ and CD8+CD27+." (PMID 39597661, 2024). "Unlike for CD8+ T cells, higher frequencies of multifunctional CCCs/SARS-CoV-2-cross-reactive memory CD4+ T cells, expressing CD69, CD107a/b, and TNF-α were detected in COVID-19 patients compared to healthy individuals." (PMID 38605956, 2024). "CD69 expression showed increased upregulation in each T cell population (CD4+ and CD8+ effector and memory T, gdT, and MAIT) in acute COVID-19 patients compared to healthy controls, suggesting that T cells were activated under inflammatory conditions." (PMID 36732528, 2023). "Improved diagnostic accuracy given by the combination of QFN with AIM (CD69, CD137, CD25, CD134) was previously seen in tuberculosis, and looks promising in COVID-19 as well." (PMID 37220145, 2023). "Various combinations of markers have been used for AIM assays in COVID-19; in agreement with others, the most of AIM+CD4+ T cells and the most of statistical correlations were herein found using CD69 and CD137." (PMID 37220145, 2023). "We demonstrate that the tetravalent S1 subunit protein COVID-19 vaccine candidate induces CD4+ and CD8+ T cell activation, as indicated by increased expression of CD69, HLA-DR, CD38, and Ki-67 activation and proliferation markers on both T cell subsets." (PMID 37830800, 2023).